FAM168A (family with sequence similarity 168 member A)
Description:
In cancer context, decreases POLB ubiquitination and stabilizes its protein levels. Acts, at least in part, through PI3K/AKT/NFKB signaling pathway and by preventing POLB degradation. Results in protection of cells from induced-DNA damage and apoptosis.
Synonyms: KIAA0280; TCRP1
Tractability: No criterion of Open Targets' tractability assessment is met for any kind of drug.
Gene: Protein-coding gene on chromosome 11 (73,400,487 to 73,598,189, reverse strand). Ensembl gene ENSG00000054965.
Subcellular location (Human Protein Atlas): Nucleoplasm
Gene Ontology:
Molecular function: protein binding
Biological process: positive regulation of base-excision repair
Genetic constraint (gnomAD): Loss-of-function variants: 3 observed, 30.3 expected, observed/expected ratio (o/e) 0.099, 90% interval 0.044 to 0.26. The upper end of that interval is the gene's LOEUF score, 0.26, which puts it in group 1 of 6, group 1 being the genes least tolerant of losing a copy. Missense variants: 222 observed, 325.59 expected, observed/expected ratio (o/e) 0.68, 90% interval 0.61 to 0.76. Synonymous variants: 122 observed, 130.17 expected, observed/expected ratio (o/e) 0.94, 90% interval 0.81 to 1.09.
Homologues: Orthologues: chimpanzee FAM168A (100% identical), macaque FAM168A (100% identical), mouse Fam168a (100% identical), dog FAM168A (99% identical), guinea pig FAM168A (99% identical), rat Fam168a (99% identical), pig FAM168A (99% identical), tropical clawed frog fam168a (92% identical), zebrafish fam168a (83% identical). Paralogues in human: FAM168B (55% identical).
Diseases named in the same sentence as FAM168A in open-access papers:
FAM168A is named in the same sentence as 19 diseases in open-access papers, as found by Europe PMC text mining. Sharing a sentence is not in itself a finding about the gene and the disease. The quoted sentences say what the papers report.
tongue cancer (8 papers, 2017 to 2024). A malignant neoplasm affecting the tongue. "FAM168A, also known as tongue cancer resistance-associated protein 1 (TCRP1) was discovered in studies of multidrug resistance of tongue cancer cells." (PMID 31291942, 2019). "In one study researchers used human toxicology and drug resistance microarray (OHS-401) in combination with immunoprecipitation to detect the gene expression profiles in FAM168A-overexpression and FAM168A-knockout tongue cancer cell lines." (PMID 31291942, 2019). "Evidence indicates that in tongue cancer cells, FAM168A, also known as tongue cancer resistance-associated protein (TCRP1), can directly bind to AKT1 and regulate AKT1/NFκB signaling pathways." (PMID 31291942, 2019).
lung carcinoma (6 papers, 2017 to 2022). "In this study, we also confirmed that TCRP1 (also known as FAM168A), a resistant relative gene in oral cancer and lung cancer is targeted regulated by miR-493." (PMID 28859669, 2017).
leukemia (1 paper, 2019). A malignant (clonal) hematologic disorder, involving hematopoietic stem cells and characterized by the presence of primitive or atypical myeloid or lymphoid cells in the bone marrow and the blood. "Immunoprecipitation results showed that FAM168A interacts with breakpoint cluster region (BCR) -Abelson murine leukemia (ABL1) fusion protein and AKT1, respectively." (PMID 31291942, 2019).
sarcopenia (1 paper, 2026). Progressive decline in muscle mass due to aging which results in decreased functional capacity of muscles. "The current study identified a novel lncRNA, A430093F15Rik, that is involved in the progression of sarcopenia by acting as a competitive endogenous RNA (ceRNA) to sponge miR-337-3p and regulate the expression of Fam168a." (PMID 41989142, 2026).
tumor (6 papers, 2012 to 2022). "FAM168A is a gene discovered in tumor drug resistance study." (PMID 31291942, 2019). "Studies show that FAM168A mediates tumor cell cisplatin resistance and radiotherapy tolerance." (PMID 31291942, 2019).
FAM168A also shares sentences with these, for which no sentence is quoted: hepatocellular carcinoma (6 papers); cancer (5); breast carcinoma (2); chronic myeloid leukemia (2); Oral Squamous Cell Carcinoma (2); ovarian carcinoma (2); colon cancer (1); glioma (1); liver cancer (1); nasopharyngeal carcinoma (1); oral cancer (1); pancreatic cancer (1); stomach cancer (1); thyroid cancer (1).